IGLV3-19 (immunoglobulin lambda variable 3-19)
Description:
V region of the variable domain of immunoglobulin light chains that participates in the antigen recognition. Immunoglobulins, also known as antibodies, are membrane-bound or secreted glycoproteins produced by B lymphocytes. In the recognition phase of humoral immunity, the membrane-bound immunoglobulins serve as receptors which, upon binding of a specific antigen, trigger the clonal expansion and differentiation of B lymphocytes into immunoglobulins-secreting plasma cells. Secreted immunoglobulins mediate the effector phase of humoral immunity, which results in the elimination of bound antigens. The antigen binding site is formed by the variable domain of one heavy chain, together with that of its associated light chain. Thus, each immunoglobulin has two antigen binding sites with remarkable affinity for a particular antigen. The variable domains are assembled by a process called V-(D)-J rearrangement and can then be subjected to somatic hypermutations which, after exposure to antigen and selection, allow affinity maturation for a particular antigen.
Synonyms: IGLV319; V2-13; VL3L
Tractability: Antibody: its Gene Ontology location is reachable by antibodies, with high confidence; UniProt places it where antibodies can reach, with medium confidence; UniProt predicts a signal peptide or a membrane-spanning region.
Gene: Immunoglobulin variable (V) gene on chromosome 22 (22,720,623 to 22,721,145, forward strand). Ensembl gene ENSG00000211663.
Subcellular location: Secreted; Cell membrane
Pathways (Reactome):
Immune System: Antigen activates B Cell Receptor (BCR) leading to generation of second messengers; CD22 mediated BCR regulation; Classical antibody-mediated complement activation; FCERI mediated Ca+2 mobilization; FCERI mediated MAPK activation; FCERI mediated NF-kB activation; FCGR activation; Fc epsilon receptor (FCERI) signaling; Immunoregulatory interactions between a Lymphoid and a non-Lymphoid cell; Initial triggering of complement; Regulation of Complement cascade; Regulation of actin dynamics for phagocytic cup formation; Role of LAT2/NTAL/LAB on calcium mobilization; Role of phospholipids in phagocytosis
Disease: FCGR3A-mediated IL10 synthesis; FCGR3A-mediated phagocytosis; Potential therapeutics for SARS
Hemostasis: Cell surface interactions at the vascular wall
Vesicle-mediated transport: Scavenging of heme from plasma
Gene Ontology:
Molecular function: antigen binding
Biological process: immune response
Cellular component: extracellular exosome; extracellular region; immunoglobulin complex; plasma membrane
Homologues: Orthologues: tropical clawed frog igl (54% identical). Paralogues in human: IGLV3-25 (73% identical), IGLV3-10 (71% identical), IGLV3-32 (71% identical), IGLV3-16 (71% identical), IGLV3-9 (70% identical), IGLV3-1 (69% identical), IGLV3-27 (68% identical), IGLV3-21 (66% identical), IGLV3-12 (64% identical), IGLV3-22 (64% identical), IGLV1-40 (63% identical), IGLV2-18 (63% identical), and 81 more.
Diseases named in the same sentence as IGLV3-19 in open-access papers:
IGLV3-19 is named in the same sentence as 4 diseases in open-access papers, as found by Europe PMC text mining. Sharing a sentence is not in itself a finding about the gene and the disease.
IGLV3-19 shares sentences with these, for which no sentence is quoted: COVID-19 (1 paper); Hepatic steatosis (1); hepatocellular carcinoma (1); infection (1).